ASS1 (argininosuccinate synthase 1)
Description:
One of the enzymes of the urea cycle, the metabolic pathway transforming neurotoxic amonia produced by protein catabolism into inocuous urea in the liver of ureotelic animals. Catalyzes the formation of arginosuccinate from aspartate, citrulline and ATP and together with ASL it is responsible for the biosynthesis of arginine in most body tissues.
Synonyms: ASS; CTLN1
Tractability: Small molecule: a structure with a bound ligand is known; it has a binding pocket of medium quality. PROTAC: ubiquitination databases record sites on it; its protein half-life has been measured.
Target class: Enzyme; Ligase
Gene: Protein-coding gene on chromosome 9 (130,443,282 to 130,502,361, forward strand). Ensembl gene ENSG00000130707.
Subcellular location: Cytoplasm, cytosol
Subcellular location (Human Protein Atlas): Cytosol; Nucleoplasm
Pathways (Reactome):
Disease: ASS1 variants cause citrullinemia
Metabolism: Urea cycle
Gene Ontology:
Molecular function: amino acid binding; argininosuccinate synthase activity; identical protein binding; protein binding; RNA binding; ATP binding; toxic substance binding
Biological process: cellular response to laminar fluid shear stress; circadian rhythm; L-arginine biosynthetic process; L-aspartate catabolic process; L-citrulline catabolic process; negative regulation of leukocyte cell-cell adhesion; positive regulation of nitric oxide biosynthetic process; urea cycle; acute-phase response; cellular response to amine stimulus; cellular response to amino acid stimulus; cellular response to ammonium ion; cellular response to cAMP; cellular response to dexamethasone stimulus; cellular response to glucagon stimulus; cellular response to lipopolysaccharide; cellular response to oleic acid; cellular response to tumor necrosis factor; cellular response to type II interferon; diaphragm development; kidney development; liver development; midgut development; response to amine; response to amino acid; and 12 more
Cellular component: cytosol; extracellular exosome; cytoplasm; cell body fiber; mitochondrial outer membrane; mitochondrion; neuronal cell body; perikaryon
Genetic constraint (gnomAD): Loss-of-function variants: 58 observed, 63.3 expected, observed/expected ratio (o/e) 0.92, 90% interval 0.74 to 1.14. The upper end of that interval is the gene's LOEUF score, 1.14, which puts it in group 4 of 6, group 1 being the genes least tolerant of losing a copy. Missense variants: 454 observed, 572.9 expected, observed/expected ratio (o/e) 0.79, 90% interval 0.73 to 0.86. Synonymous variants: 200 observed, 216.01 expected, observed/expected ratio (o/e) 0.93, 90% interval 0.82 to 1.04.
Gene-disease validity (ClinGen):
ClinGen rates the evidence that ASS1 causes each of these diseases.
citrullinemia type I (autosomal recessive): Definitive.
Homologues: Orthologues: chimpanzee ASS1 (99% identical), macaque ASS1 (99% identical), dog ASS1 (98% identical), rat Ass1 (98% identical), pig ASS1 (97% identical), guinea pig ASS1 (97% identical), mouse Ass1 (97% identical), tropical clawed frog ass1 (80% identical), Drosophila melanogaster Ass (55% identical), zebrafish ASS1 (47% identical).
Diseases named in the same sentence as ASS1 in open-access papers:
ASS1 is named in the same sentence as 183 diseases in open-access papers, as found by Europe PMC text mining. Sharing a sentence is not in itself a finding about the gene and the disease. The quoted sentences say what the papers report.
melanoma (57 papers, 2012 to 2026). A malignant, usually aggressive tumor composed of atypical, neoplastic melanocytes. "Pegargiminase is a pegylated arginine deiminase that depletes circulating arginine, a critical amino acid for the growth of argininosuccinate synthetase 1 (ASS1)-deficient tumors, including melanoma and glioblastoma." (PMID 41041285, 2025). "When this medicament was used against glioma-, melanoma- or other ASS1 deficient malignancies, a similar rise of citrulline has been noted." (PMID 34444954, 2021). "Majority of the lung and colon carcinomas show ASS1 expression, while melanoma, hepatocellular carcinoma and prostate carcinomas are frequently ASS1-deficient." (PMID 28187218, 2017). "One study showed that under normoxia, arginine-deprivation inhibited basal HIF-1α expression in ASS1-deficient melanoma cells." (PMID 26972697, 2016). "Comparison of the efficacy of ONCOS-212 in subgroups of patients with melanomas that differ in ASS1 status probably could inform the susceptible cohorts." (PMID 36816748, 2023). "However, BRAFi-resistant melanomas are susceptible to arginine deprivation due to their inability to re-express ASS1 and by causing ineffective autophagy, where autophagy promotes melanoma tumor progression." (PMID 37445845, 2023). "Such therapies are in phase I of clinical studies in combination with immune checkpoint inhibitor antibodies, in the context of argininosuccinate synthase 1 (ASS1)—deficient cancers, normally melanoma, lymphoma, glioma or prostate cancers that rely on circulating arginine." (PMID 33915900, 2021). "Notably, favorable results have been obtained from clinical trials using pegylated arginine deiminase (ADI-PEG20; Feun and Savaraj, 2006) to treat ASS1-deficient cancers including hepatocellular carcinoma and advanced melanoma." (PMID 23643539, 2013). "Argininosuccinate synthetase-1 (ASS-1), a rate-limiting enzyme in de novo arginine biosynthesis, has been reported to be downregulated in hepatocarcinoma and prostate cancer, as well as in malignant melanoma and to be associated with advanced tumor stages and poor survival rates." (PMID 35955892, 2022). "However, a number of human cancers, including melanoma, hepatocellular carcinoma and prostate carcinoma, are defined as auxotroph for arginine, indicating that these tumours are unable to synthesise arginine de novo, due to ASS1 deficiency." (PMID 33809510, 2021). "ATF4 knockout in melanoma cells phenocopied ASS1 knockout in the same cells, both showing greater sensitivity to arginine depletors such as ADI-PEG20." (PMID 41867829, 2026). "Both Atf4 and Ass1 knockout melanomas exhibited enhanced infiltration of Cd8+ T cells and significantly reduced tumor growth in a syngeneic mouse model." (PMID 41867829, 2026). "We therefore depleted ASS1-low melanoma cell lines (A375 and SK-MEL-28) from arginine via treatment with arginine deiminase (ADI), an enzyme catalyzing the degradation of arginine, and subjected total RNA to RNA004 tRNA-seq." (PMID 41190243, 2025). "A range of malignancies, including melanoma, glioblastoma, and pancreatic, colorectal, and hepatocellular carcinomas, are characterized by a reduced expression of ASS1, resulting in a dependence on extracellular L-arg." (PMID 41295280, 2025). "The authors found that cancers with low expression of argininosuccinate synthase (ASS1), such as malignant melanoma and small cell lung cancer, were particularly sensitive to pegzilarginase treatment." (PMID 40356601, 2025). "In ASS1-deficient leiomyosarcoma (SKLMS1, SKUT1) and melanoma (SKMEL2) cells, arginine deprivation suppresses the Warburg effect while promoting OXPHOS." (PMID 40507936, 2025). "On the other hand, some cancers, including melanoma and hepatocellular carcinoma, have been shown to downregulate ASS1 expression, leading to arginine depletion in the tumor microenvironment." (PMID 39330508, 2024).
melanoma (continued). "Some primary melanomas express ASS1 and appear less sensitive to arginine deprivation as evidenced in a clinical trial of ADI-Peg." (PMID 36816748, 2023). "ADI-PEG 20 can induce transcriptional activation of the rate-limiting enzyme ASS1 in some melanoma cell lines and combining it with TRAIL enhances apoptosis and accelerates cell death in vitro." (PMID 37445845, 2023). "Re-expression or upregulation of ASS1 can be the main molecular mechanism of resistance in melanoma and quite a few other cancers." (PMID 34299249, 2021). "The somatic silence or down-regulation of ASS1 expression are very common in various of tumors, including melanoma, prostate cancer, breast cancer, bladder cancer, mesothelioma, pancreatic cancer, nasopharyngeal carcinoma, osteosarcomas, and myxofibrosarcomas." (PMID 33859183, 2021). "By studying induced-resistant melanoma cell lines, the investigators found that these cells had lowered mTOR activity but enhanced glycolysis in addition to upregulated ASS1 expression." (PMID 34299249, 2021). "By contrast, arginine deprivation of ASS1-low melanoma and sarcoma cells leads to downmodulation of glycolysis pathway with increased glutamine anaplerosis and serine synthesis to sustain the TCA cycle." (PMID 34298755, 2021). "In a BRAFi resistant melanoma cell model, c-myc proteins were actively degraded, that led to in-ability to re-express ASS1." (PMID 28750681, 2017). "It has been reported that naïve melanoma cells undergo autophagy and re‐express argininosuccinate synthetase 1 (ASS1) to enable them to synthesize arginine for survival when encountering arginine deprivation." (PMID 29094484, 2017). "Melanomas are auxotrophic for arginine due to the reduced expression of argininosuccinate synthetase-1 (ASS1), which is the rate-limiting enzyme for arginine biosynthesis." (PMID 26116372, 2015). "Interestingly, while ASS1 loss is due to promoter methylation in MPM cells, reduced ASS1 expression has been shown to be mediated by c-Myc and HIF-1α in other cancers including melanoma." (PMID 39758821, 2025). "Strategies such as arginine deiminase and human arginase (hArg) exploit arginine auxotrophy in tumors, particularly those with deficiencies in arginosuccinate synthesis 1 (ASS1) or ornithine transcarbamylase (OCT), including hepatocellular carcinoma and melanoma." (PMID 41295280, 2025). "The results showed that ADI-PEG 20 is safe and effective in melanoma patients with negative ASS1 expression, while ASS1 positivity is associated with drug resistance and tumor progression." (PMID 37445845, 2023). "Studies using melanoma cell lines revealed that the suppression of ASS1 expression is due to Hif1α binding to the promoter region of ASS1, but this suppression can be relieved under ADT by induced downregulation of Hif1α and binding of upregulated c-Myc to replace Hif1α." (PMID 34299249, 2021). "Reduced expression of arginosuccinate synthase 1 (ASS1) has been observed in melanoma, glioma, lymphoma, and prostate cancer, and arginine deprivation therapy may generate antitumor efficacy in these cancer cells due to ASS1-involved arginine synthesis." (PMID 32509584, 2020). "Therefore, BRAFi-resistant melanoma cells expressed very low level of ASS1 and were very sensitive to ADI-PEG20 in vivo." (PMID 28750681, 2017). "Similarly, melanoma tumorcells have been reported to display constitutively high levels of ASS1 expressionafter ADI treatment." (PMID 25928182, 2015). "However, many tumor types, such as melanoma, hepatocellular carcinoma, and pancreatic cancer, are arginine auxotrophic because of silencing in ASS1 expression, which means the cancer cells are devoid of endogenous arginine and therefore have a critical dependence on exogenous arginine." (PMID 35941558, 2022). "The basal expression of ASS1 is particularly low in malignant melanoma, however the half inhibitory concentration (IC50) and ASS1 are significantly increased after ADI treatment for a long time." (PMID 41460862, 2025).
melanoma (continued). "Cisplatin is another cytotoxic agent shown preclinically to enhance the effects of ADI-PEG20 by inhibition of DNA repair and ASS1 suppression by upregulation of HIF-1α and downregulation of c-Myc in melanoma cell lines." (PMID 36903394, 2023). "Many tumors, including HCC, malignant melanoma, malignant pleural mesothelioma, and prostate and renal cancers, are arginine auxotrophic due to their variable loss of argininosuccinate synthase 1 (ASS1), which is severely reduced or absent in numerous types of aggressive and chemoresistant cancers." (PMID 33838671, 2021). "In another study of ADI-resistance using melanoma cell lines, all ADI-resistant cells displayed enhanced ASS1, GLS1, and GDH protein expressions mediated by up-regulated c-myc, comparing to parental cell lines." (PMID 28750681, 2017). "In melanoma cells, hypoxia-inducible factor (HIF-1α)-mediated transcriptional repression of ASS1 has been observed." (PMID 25164070, 2014). "It was previously reported that the acquired resistance to rhARG1 in melanoma cells in vivo was due to the altered expression of the two transcription factors c-Myc and HIF-1α, which are positive and negative regulators, respectively, of ASS1 gene expression." (PMID 40563540, 2025). "A lack of ASS1 expression or ASS1 downregulation is very common in cancer, including myxofibrosarcomas, breast cancer, malignant melanoma, liver cancer, prostate cancer, pancreatic cancer, renal cancer, and osteosarcomas." (PMID 38710705, 2024). "Approximately 70% of primary melanomas do not express argininosuccinate synthetase-1 (ASS1), which produces arginine." (PMID 36816748, 2023). "The specific mechanism of the adaptive transcriptional upregulation of ASS1 and ASL is unknown, but studies in melanoma suggest that accumulated cMyc can induce ASS1 expression by interacting with the ASS1 promoter." (PMID 35898872, 2022). "It has been found that in many cancers, including melanoma, hepatocellular carcinoma, and prostate cancer, the incidence of low or negative expression of ASS1 is prevalent." (PMID 34299249, 2021). "Apart from the upregulation of ASS1, reprogramming of tumor cell metabolism may also contribute to the resistance to ADI-PEG20 in melanoma." (PMID 34299249, 2021). "In our former investigation, we found that arginine deprivation can efficiently enhance TRAIL toxicity in melanoma cell lines which do not express argininosuccinate synthetase (ASS1)." (PMID 34299249, 2021). "In one clinical study, two patients with initial ASS1-negative melanoma under ADI-PEG20 treatment were found to be ASS1-positive after tumor progression." (PMID 34299249, 2021). "In a study of ASS1-low melanomas, regardless of the BRAF status, arginine deprivation down-modulates FANCD2 and p-ATM, which are important initiators for DNA double strand break repair." (PMID 34298755, 2021). "For tumors of which the ASS1 promoter is not methylated (e.g., melanoma and sarcoma), the activation of c-Myc oncogene which drives the expression of ASS1 appears to be the underlying cause." (PMID 34298755, 2021). "In these mice, ASS1-low syngeneic murine melanoma cells failed to grow with the infiltration of CD8 positive cells, indicating the T cell immune response is not severely affected by systemic depletion of arginine." (PMID 34298755, 2021). "It has been reported that ADI inhibits the growth of several ASS1-negative tumors, such as melanoma and hepatocellular carcinoma (HCC), suggesting that it has potential as an anti-cancer agent." (PMID 32353864, 2020). "The result showed that ASS1 overexpression significantly downregulated CAT‐2 rather than CAT‐1 in these melanoma cells." (PMID 29094484, 2017). "Furthermore, expression of ASS1, AMPK‐α1, or RNF44 represented as H‐score confirmed that BR/BMR tumor samples had 2‐7‐fold lower ASS1 and AMPK‐α1 than the average levels but fivefold higher RNF44 compared to naïve melanoma samples." (PMID 29094484, 2017).
melanoma (continued). "As these four melanoma cells did not express ASS1 they might be more sensitive to arginine deprivation induced by local expression of PADI1." (PMID 36816748, 2023). "Multiple melanoma and breast cancer cell lines have been shown to become more resistant to glutamine deprivation as ASS1 expression increased in the absence of arginine starvation, whereas loss of ASS1 sensitizes cells to combined arginine and glutamine starvation." (PMID 35582579, 2019). "Therefore, these melanoma cells lacking ASS1 expression must acquire exogenous arginine to support biosynthesis of polyamines and other amino acids for protein synthesis." (PMID 29094484, 2017). "Interestingly, ADI-PEG20 did not increase ASS1 protein in the time frames reported in melanoma cells." (PMID 26972697, 2016). "Intriguingly, drug resistance is an important contributor for treatment failure of ASS1-negative tumors by ADI-PEG 20, possibly due to re-expression of the once-silenced ASS1 that has been observed in melanoma cell lines." (PMID 25164070, 2014). "The results showed that patients with negative ASS1 expression had a higher clinical benefit rate and a longer time to progression compared to patients with positive ASS1 expression, suggesting that ADI-PEG 20 is only effective in melanoma patients whose tumors have negative ASS1 expression." (PMID 37445845, 2023). "Early resistance may also have accounted for the negative results with ASS1 re-expression documented in trials of ADI-PEG20 monotherapy and maintenance in patients with melanoma and thoracic cancers, respectively, and consistent with earlier preclinical data." (PMID 36903394, 2023). "Interestingly, we identified that in the primary cases with focal ASS1 expression (5%–30%) the majority of cells with the highest expression were in fact CD68‐positive macrophages (or melanophages) and not melanoma cells." (PMID 35466524, 2022).